U3 (Small nucleolar RNA U3 )
Synonyms: LOC124905065
Gene: Small nucleolar RNA gene on chromosome 21 (29,180,425 to 29,180,639, reverse strand). Ensembl gene ENSG00000212479.
Gene Ontology:
Biological process: RNA processing
Cellular component: nucleolus
Homologues: Orthologues: chimpanzee U3 (95% identical), macaque U3 (88% identical), rabbit U3 (60% identical), rat LOC120102769 (56% identical). Paralogues in human: SNORD3P1 (77% identical), U3 (77% identical), U3 (76% identical), SNORD3G (74% identical), U3 (74% identical), U3 (73% identical), SNORD3E (73% identical), U3 (72% identical), SNORD3H (71% identical), U3 (71% identical), SNORD3D (70% identical), U3 (69% identical), and 10 more.